FH (fumarate hydratase)
Diseases named in the same sentence as FH in open-access papers (continued):
Sharing a sentence is not in itself a finding about the gene and the disease.
Uterine leiomyoma (continued). "To assess the role of FH and the linked genes in nonsyndromic uterine fibroids, we explored a two-megabase interval spanning FH in the NIEHS Uterine fibroid study, a cross-sectional study of fibroids in 1152 premenopausal women." (PMID 23555580, 2013). "Patients with hereditary leiomyomatosis and RCC (HLRCC) have a mutation in the gene encoding the Krebs cycle enzyme fumarate hydratase (FH), and are at risk of developing cutaneous and uterine leiomyomas and an aggressive phenotype of type 2 pRCC." (PMID 22738081, 2011). "In 2002, the Multiple Leiomyoma Consortium identified heterozygous germline mutations of FH in patients with multiple cutaneous and uterine leiomyomas, (MCUL: OMIM 150800)." (PMID 18366737, 2008). "Female FH mutation carriers are also at high risk of early-onset uterine fibroids that frequently require hysterectomy." (PMID 18366737, 2008). "To evaluate fumarate hydratase in respective sporadic tumours, we analysed a series of 26 leiomyosarcomas and 129 uterine leiomyomas (from 21 patients) for somatic mutations in fumarate hydratase and allelic imbalance around 1q43." (PMID 12177782, 2002). "To evaluate the role of FH in sporadic leiomyomas and leiomyosarcomas, we analysed 129 uterine leiomyomas and 26 leiomyosarcomas for somatic mutations and allelic imbalance at 1q42.3-q43." (PMID 12177782, 2002). "On MRI, FH-deficient leiomyomas may present imaging features distinct from those of conventional uterine leiomyomas." (PMID 41438660, 2026). "Due to metabolic abnormalities caused by FH gene variants, uterine fibroids in patients with HLRCC may have a greater proliferative capacity and a higher risk of malignancy." (PMID 40899374, 2025). "Uterine leiomyomas are present in 73%–100% of women with FH mutations and may cause symptoms such as menorrhagia and reproductive dysfunction." (PMID 39282017, 2024). "It is speculated that for HRLCC infertility women with multiple uterine leiomyomas, preimplantation genetic testing may help block transmission of mutated FH gene during pregnancy." (PMID 38933105, 2024). "The final pathologic report proved the uterine leiomyoma lesions to be FH-deficient as expected." (PMID 36981015, 2023). "We found the FH missense variant c.1132G > A could activate cell proliferation in uterine leiomyoma cell lines as expected." (PMID 36981015, 2023). "Uterine leiomyomas (ULMs) are highly penetrant as 73% to 100% of women with the FH mutation are affected by the common symptoms including menorrhagia, irregular menstruation, pain and reproductive dysfunction which often lead to infertility and pregnancy complications." (PMID 35163394, 2022). "Our study reports the FH missense mutation c.557G>A results in the uterine leiomyomas phenotype." (PMID 35163394, 2022). "This case report describes a woman with multiple uterine leiomyomas diagnosed with FH deficiency." (PMID 34889279, 2021). "Pathological examination showed multiple, cellular, and bizarre nucleus leiomyomas, as well as cytoplasmic eosinophilic globules and staghorn vessels, which were consistent with previously reported morphological characteristics of FH-deficient uterine leiomyomas." (PMID 34889279, 2021). "Gynecologists should be aware that early onset uterine leiomyoma presenting as large, multiple, and symptomatic lesion, may be associated with FH deficiency." (PMID 34889279, 2021). "HLRCC is an autosomal dominant condition characterized by germline mutations in the fumarate hydratase (FH) gene, and susceptible individuals are at risk for developing cutaneous and uterine leiomyomas, as well as an aggressive form of type 2 papillary renal cell carcinoma." (PMID 33946504, 2021). "In Case #1, we suspect that the FH mutation is segregating with the patient's maternal family, given the confirmed diagnosis of his cousin's early onset kidney cancer at age 40 and given his mother's reported history of uterine leiomyomas." (PMID 32463173, 2020).
Uterine leiomyoma (continued). "Indeed, FH deficiency in uterine leiomyomas, or fibroids, presents clinically as multiple, large, and symptomatic benign tumors that may differ significantly from sporadic leiomyomas." (PMID 40002168, 2025). "Thus, it could be suggested that the mechanism of FH mutation c.557G>A underlies uterine leiomyomas was due to the impaired mTOR signaling and autophagy." (PMID 35163394, 2022). "In addition FH mutations have also been described in case of uterine fibroids." (PMID 23320739, 2013). "Uterine leiomyomas are benign smooth muscle tumors of the uterus and are influenced by genetic alterations, including those in the FH gene." (PMID 40002168, 2025). "Genetic testing is essential for diagnosing FH mutations, especially in individuals with a family history of HLRCC or those presenting with multiple cutaneous and uterine leiomyomas." (PMID 40002168, 2025). "Three main uterine leiomyoma molecular subtypes include tumors with MED12 mutation, molecular aberrations leading to HMGA2 overexpression, and biallelic loss of FH." (PMID 37466765, 2024). "It has been shown that three main uterine leiomyoma molecular subtypes exist, including tumors with MED12 mutation, molecular aberrations leading to HMGA2 overexpression, and biallelic loss of FH." (PMID 37466765, 2024). "This analysis confirmed that mutations in FH and MED12 co-exist for the first time in uterine fibroids in Australian women." (PMID 37113812, 2023). "Patients with infertility who are offered genetic testing should be screened for FH mutations, as the carriers are at risk of developing HLRCC-associated uterine fibroids, which can influence fertility and pregnancy." (PMID 37663422, 2023). "Uterine leiomyomas are benign smooth muscle tumors that can be classified into at least three molecular subtypes, reflecting mutations in either MED12, HMGA2, or FH." (PMID 36068196, 2022). "We and others have shown that overexpression of AKR1B10 can function as a biomarker for FH-deficiency and NRF2 activation in uterine leiomyomas and renal cell cancer." (PMID 36068196, 2022). "In this study, we present a novel uterine leiomyoma subtype that is FH-proficient but displays AKR1B10 protein expression." (PMID 36068196, 2022). "We also analysed SNPs on driver genes such as MED12, FH, and HMGA2 which harbor somatic mutations in uterine leiomyoma." (PMID 31988393, 2020). "Another individual had previously been investigated with germline FH sequencing after the diagnosis of multiple cutaneous leiomyomas and a family history of a first-degree relative undergoing a hysterectomy for uterine leiomyomas." (PMID 29909963, 2018). "Studies estimate that germline mutations in FH account for a significant percentage of FH-negative uterine leiomyomas in younger patients (up to 30 years of age)." (PMID 40002168, 2025). "Genetic alterations associated with uterine leiomyoma are heterogeneous and they include mutations of mediator complex subunit 12 (MED12), overexpression of high mobility group AT-hook 2 (HMGA2), and inactivation of the fumarate hydratase (FH) gene." (PMID 38642139, 2024). "In their study, 18 (81.8%) patients had multiple leiomyomas (ranging from 2 to 14 cm) and 0.4% of uterine leiomyomas were proved to be FH-deficient, while none presented as leiomyosarcoma." (PMID 36981015, 2023). "The hereditary form is associated with biallelic inactivation of the gene encoding the Krebs cycle enzyme fumarate hydratase (FH), which leads to hereditary leiomyomatosis and RCC (HLRCC) syndrome, which is characterized by a high incidence of RCC, uterine leiomyoma, and cutaneous leiomyomatosis." (PMID 36927438, 2023). "Recent literature has shown that uterine leiomyomas with FH mutations do not always show consistent changes to cellular morphology nor are IHC stains particularly sensitive or specific in diagnosing HLRCC." (PMID 37663422, 2023).
Uterine leiomyoma (continued). "In addition, uterine leiomyoma harbors genetic alteration of some driver genes including MED12 mutations, biallelic inactivation of FH, and HMGA2 rearrangements." (PMID 31988393, 2020). "Finally, FH expression evaluated by immunohistochemistry was conserved on the uterine leiomyoma and pelvic leiomyosarcoma of the proband, which strongly suggests the absence of somatic pathogenic variants of FH responsible for these 2 tumors in the proband." (PMID 33112832, 2020). "Although not employed currently as a routine clinical screening method for HLRCC, we acquired an antibody directed against FH (J-13 fumarate hydratase, Santa Cruz Biotechnology, Santa Cruz, CA) and performed staining on the lesion using two benign uterine leiomyomas as positive controls." (PMID 27529047, 2016). "Although uterine fibroids are the most common tumors in women during their reproductive years, FH mutations do not appear to play a major role in non-syndromic cases." (PMID 18366737, 2008). "Our findings indicate that mutations in fumarate hydratase do not play a major role in the development of sporadic leiomyosarcomas or uterine leiomyomas." (PMID 12177782, 2002). "Moreover, certain FH mutations have been associated with the development of uterine fibroids in the absence of cutaneous leiomyomas." (PMID 37663422, 2023). "Certain FH mutations have also been associated with uterine fibroids without skin leiomyomas." (PMID 18366737, 2008). "FH-Wild type (FH-WT) and FH-mutant (FH-MUT) (E378K) plasmid were constructed and transfected into 293T and uterine leiomyoma cell lines, respectively." (PMID 36981015, 2023). "While numerous studies have outlined a plausible role of FH in syndromic uterine leiomyomas, its involvement in non-syndromic uterine leiomyomas remains obscure." (PMID 38790186, 2024). "Immunohistochemistry results demonstrated that cells of uterine leiomyoma were negative for FH, while adjacent vascular endothelial cells and vascular smooth muscle cells were positive for FH." (PMID 34889279, 2021).
leiomyoma (58 papers, 2002 to 2026). A well-circumscribed benign smooth muscle neoplasm characterized by the presence of spindle cells with cigar-shaped nuclei, interlacing fascicles, and a whorled pattern. "In this report, we describe the case of a 44-year-old woman diagnosed with an FH-deficient leiomyoma, underlining both the diagnostic challenges and the importance of recognizing potential genetic associations." (PMID 41438660, 2026). "These cases illustrate the diagnostic complexity of FH-deficient leiomyomas and underscore the barriers to genetics-based care in Appalachia." (PMID 41585615, 2026). "Maintaining a strong clinical suspicion can facilitate the identification of FH-deficient leiomyomas and, importantly, help uncover cases associated with HLRCC, enabling timely genetic evaluation and early management." (PMID 41438660, 2026). "FH-deficient leiomyomas exhibit distinctive microscopic characteristics that aid in their recognition." (PMID 41438660, 2026). "Among them, fumarate hydratase (FH)–deficient leiomyomas represent a rare variant, reported in about 0.4%-1% of all cases." (PMID 41438660, 2026). "The patient underwent polymyomectomy, and histopathological analysis identified an Fumarate hydratase (FH)-deficient leiomyoma." (PMID 41438660, 2026). "Accurate histopathological identification of FH-deficient leiomyomas is crucial, as it not only ensures correct diagnosis but also raises the need for further clinical and genetic evaluation." (PMID 41438660, 2026). "This patient’s presentation with rapidly enlarging symptomatic fibroids is consistent with the more aggressive phenotype described in the literature for FH-deficient cases." (PMID 41585615, 2026). "In one case, neither of the found P/LP variants explained the phenotype: a patient with FH-deficient leiomyoma had P/LP variants in CDH1 and ATM (case #16)." (PMID 40943312, 2025). "Management of FH-deficient leiomyomas includes conventional treatments for fibroids, such as surgical removal or hormonal therapy, but with additional considerations due to the potential for associated malignancies." (PMID 40002168, 2025). "Genetic screening and morphological evaluation are essential for the identification and management of FH-deficient leiomyomas, as these entities are rare." (PMID 40002168, 2025). "Formal genetic testing is recommended in patients with FH-deficient leiomyomas to identify HLRCC cases." (PMID 41000563, 2025). "FH mutations are present in approximately 0.4–1.6% of all uterine fibroids, and the estimated carrier frequency of pathogenic FH variants in the general population is about 1 in 2563 individuals." (PMID 41300720, 2025). "Of the 10 cases with double P/LP variants in HBOC genes, eight had breast cancer, one had prostate cancer, and one had a fumarate hydratase (FH)-deficient leiomyoma with a family history of breast cancer." (PMID 40943312, 2025). "Studies have reported a strong association between leiomyomas with bizarre nuclei, notable cytonuclear atypia, and FH deficiency." (PMID 38793008, 2024). "This is because retained FH staining has been observed in uterine leiomyomas with an FH germline mutation." (PMID 38793008, 2024). "Nevertheless, studies have confirmed that the majority of leiomyomas with such bizarre features exhibit reliable specific FH immunoexpression, indicating its deficiency." (PMID 38793008, 2024). "The median age of patients presenting with FH-deficient leiomyomas is approximately ten years younger than that of patients presenting with sporadic ones." (PMID 38793008, 2024). "FH deficient leiomyomas have been uniquely shown to activate nuclear factor erythroid 2-related factor 2 (NRF2) target genes based on the excess of fumarate." (PMID 38957794, 2024). "Overall, the FH mutation (c.557G>A) overexpressed cells exhibited similar cellular phenotypes as FH-deficient uterine leiomyomas cells." (PMID 35163394, 2022).
leiomyoma (continued). "In contrast to FH-deficient leiomyomas that also display NRF2 activation, but presumably functional neddylation, we identified the deubiquitin gene UCHL1 as one of the most uniquely upregulated genes in AKR1B10hi tumors." (PMID 36068196, 2022). "Most tumors displayed cellular histopathology, perivascular hypercellularity, and characteristics typically seen in FH-deficient leiomyomas." (PMID 36068196, 2022). "Histopathological features associated with FH-deficiency are typically seen in leiomyomas with bizarre nuclei, but rarely in leiomyomas with cellular histopathology." (PMID 36068196, 2022). "As we detected biallelic loss of FH in two leiomyomas previously reported to overexpress HMGA1, we explored the expression pattern of HMGA1 in our dataset as well." (PMID 33352722, 2020). "Cutaneous leiomyomas, especially if multiple, are pathognomonic and FH-deficient RCC in young adults before age 50 years also raises a strong suspicion for HLRCC." (PMID 32612247, 2020). "Mutations of MED12 and/or FH, which are common in leiomyoma and show high VAFs, have been reported in ~10% of adenomyosis and adenomyotic polyps." (PMID 31857578, 2019). "MED12 mutations were the most common alterations in conventional and mitotically active leiomyomas and leiomyosarcomas, while leiomyomas with bizarre nuclei were most often FH deficient and cellular tumors showed frequent HMGA2 overexpression." (PMID 28592321, 2017). "FH deficiency has been shown to be overrepresented in leiomyomas with bizarre nuclei and some of the morphologic features typical for these tumors have been associated with FH mutations." (PMID 28592321, 2017). "Again, this illustrates the potential of WGS and multi-gene panels to identify co-occurring cancer gene mutations (e.g. RAD51C and FH) that pose genetic risks (breast/ovarian cancer) beyond the patient's primary diagnosis (leiomyoma)." (PMID 26023681, 2015). "Inactivating FH mutations have rarely been observed in the nonsyndromic and common form of fibroids; however, loss of heterozygosity across FH appeared as a significant event in the pathogenesis of a subset of these tumors." (PMID 23555580, 2013). "Mutations in the Krebs cycle enzyme, fumarate hydratase (FH), predispose affected individuals to leiomyomas, renal cysts, and cancers, though the respective pathogenic roles of mitochondrial and cytosolic FH isoforms remain undefined." (PMID 23643539, 2013). "Rare hereditary leiomyomatosis and renal cell carcinoma syndrome (HLRCC [MIM 150800]) is caused by heterozygous germline mutations in the gene encoding fumarate hydratase, but the role(s) of individual genes in common leiomyomas is not well understood." (PMID 22428002, 2012). "It had been reported that individuals with loss of FH activity are at risk for the development of leiomyomas of the skin and uterus (fibroids) as well as kidney cancer." (PMID 22087286, 2011). "Individual considered affected by HLRCC had greaterthan 10 skin lesions clinically compatible with leiomyoma and a minimum of 1lesion histologically confirmed as leiomyoma or tested positive for a germline FH mutation." (PMID 18695737, 2008). "Mutations in the fumarase hydratase (FH) gene, an enzyme which is involved in the mitochondrial tri-carboxylic acid cycle, are known to cause leiomyomas." (PMID 16223449, 2005). "There are several possible reasons for the low frequency of FH mutations in sporadic leiomyomas and leiomyosarcomas detected in our study." (PMID 12177782, 2002). "Prompted by the predisposition to leiomyomata and leiomyosarcoma seen in carriers of germline mutations in FH we have screened the full coding sequence and splice junctions of FH for somatic mutation in a series of sporadic leiomyomas and leiomyosarcomas." (PMID 12177782, 2002). "From a clinical perspective, the recognition of FH-deficient leiomyomas has major implications." (PMID 41438660, 2026). "Immunohistochemical staining confirmed FH-deficient leiomyoma." (PMID 41585615, 2026).